AP1S2 (adaptor related protein complex 1 subunit sigma 2)
Description:
Subunit of clathrin-associated adaptor protein complex 1 that plays a role in protein sorting in the late-Golgi/trans-Golgi network (TGN) and/or endosomes. The AP complexes mediate both the recruitment of clathrin to membranes and the recognition of sorting signals within the cytosolic tails of transmembrane cargo molecules.
Synonyms: DC22; SIGMA1B; MRX59; MRXS21; MRXS5; MRXSF; PGS
Tractability: Antibody: UniProt places it where antibodies can reach, with medium confidence. PROTAC: ubiquitination databases record sites on it; its protein half-life has been measured.
Gene: Protein-coding gene on chromosome X (15,825,806 to 15,854,931, reverse strand). Ensembl gene ENSG00000182287.
Subcellular location: Golgi apparatus; Cytoplasmic vesicle membrane; Membrane, clathrin- coated pit
Subcellular location (Human Protein Atlas): Golgi apparatus; Vesicles
Pathways (Reactome):
Vesicle-mediated transport: Golgi Associated Vesicle Biogenesis; Lysosome Vesicle Biogenesis
Disease: Nef mediated downregulation of MHC class I complex cell surface expression
Immune System: MHC class II antigen presentation
Gene Ontology:
Molecular function: protein binding; clathrin adaptor activity
Biological process: melanosome assembly; platelet dense granule organization; vesicle-mediated transport; intracellular protein transport; protein transport
Cellular component: Golgi apparatus; AP-1 adaptor complex; AP-type membrane coat adaptor complex; cytoplasmic vesicle membrane; cytosol; early endosome; Golgi membrane; lysosomal membrane; trans-Golgi network membrane; clathrin-coated pit; membrane coat
Homologues: Orthologues: guinea pig AP1S2 (100% identical), macaque AP1S2 (100% identical), pig AP1S2 (100% identical), tropical clawed frog ap1s2 (100% identical), chimpanzee AP1S2 (91% identical), zebrafish ap1s2 (91% identical), mouse Ap1s2 (90% identical), rabbit AP1S2 (90% identical), rat Ap1s2 (90% identical), dog AP1S2 (86% identical), Drosophila melanogaster AP-1sigma (79% identical), Caenorhabditis elegans aps-1 (76% identical). Paralogues in human: AP1S1 (85% identical), AP1S3 (69% identical), AP2S1 (42% identical), AP3S1 (37% identical), AP3S2 (36% identical), AP4S1 (34% identical).
Diseases named in the same sentence as AP1S2 in open-access papers:
AP1S2 is named in the same sentence as 38 diseases in open-access papers, as found by Europe PMC text mining. Sharing a sentence is not in itself a finding about the gene and the disease. The quoted sentences say what the papers report.
melanoma (13 papers, 2013 to 2025). A malignant, usually aggressive tumor composed of atypical, neoplastic melanocytes. "LINC00518, miR-204-5p and AP1S2 were found to have underlying correlation in melanoma." (PMID 31712557, 2019). "miR-204 is regulated by STAT3 in amelanotic melanoma cells, where it targets AP-1 complex subunit sigma-2 (AP1S2) and inhibits motility." (PMID 38672652, 2024). "Previous studies reported that compared with NMM, the expression levels of SNAI2, MMP2, MIF, and AP1S2 were up-regulated in MM and were crucial roles in the metastasis and malignant progression of melanoma." (PMID 37880239, 2023). "LINC00518 (p-value = 0.00803) has shown to act as a competing endogenous RNA to promote the metastasis of malignant melanoma via miR-204-5p/AP1S2 axis." (PMID 33392203, 2020). "In conclusion, these results suggested that LINC00518 promotes AP1S2 expression by competitive binding miR-204-5p in melanoma." (PMID 31712557, 2019). "LINC00518 siRNA also led to a decrease in the mRNA and protein levels of AP1S2 in melanoma cells, and this inhibition was reversed by cotransfection with miR-204-5p inhibitor." (PMID 31712557, 2019). "LINC00518 facilitates melanoma metastasis by sponging miR-204-5p to release AP1S2 mRNA transcripts targeted by miR-204-5p, thereby promoting the AP1S2 expression." (PMID 31712557, 2019). "In this study, we further confirmed the antimotility role of miR-204-5p and the pro-motility role of AP1S2 in melanoma." (PMID 31712557, 2019). "AP1S2, a validated pro-motility target, has been shown to facilitate the migration and invasion of melanoma cells." (PMID 31712557, 2019). "These revealed that LINC00518 modulates the metastasis of melanoma cells through sponging miR-204-5p to promote AP1S2 expression." (PMID 31712557, 2019). "Simultaneously, LINC00518 siRNA, AP1S2 siRNA and miR-204-5p mimic inhibited melanoma cell infiltration in a 3D collagen matrix, these melanoma cells showed a less invasive morphology." (PMID 31712557, 2019). "Lastly, we also showed that LINC00518 also promotes melanoma metastasis in vivo by regulating the expression of AP1S2." (PMID 31712557, 2019). "Meanwhile, we found a negative correlation between LINC00518 and miR-204-5p levels, and a positive correlation between LINC00518 and AP1S2 mRNA levels in 36 melanoma tissues." (PMID 31712557, 2019). "Overall, it demonstrated that LINC00518 modulates metastasis of melanoma cells by sponging miR-204-5p to promote AP1S2 expression." (PMID 31712557, 2019). "miR-204 is under the control of STAT3 and its expression is induced in amelanotic melanoma cells, where it acts as an effector of vemurafenib's anti-motility activity by targeting AP1S2." (PMID 28445987, 2017). "Altogether these results indicate that, in amelanotic melanoma cells, miR-204 is induced by BRAFi/MEKi and favors its anti-migratory activity by targeting AP1S2." (PMID 28445987, 2017). "Additionally, LINC00518 indirectly promotes AP1S2 via miR-204–5p in melanoma, playing a crucial role in disease progression." (PMID 39108268, 2024). "Finally, the expression levels of SNAI2, MMP2, MIF, and AP1S2 were elevated in melanoma cells of MM, consistent with the results of previous studies." (PMID 37880239, 2023). "Similarly, it was found that LINC00518 promoted the migration, invasion, and metastasis of melanoma through the miR-204-5p/AP1S2 and miR-33a-3p/HIF-1α axes, which is consistent with our finding that LINC00518 serves as a risk factor for SKCM." (PMID 36371574, 2022). "In addition, LINC00518 promotes the invasion and migration of melanoma cells through regulating Adaptor Related Protein Complex 1 Sigma 2 Subunit (AP1S2), by binding miR-204-5p, that targets AP1S2." (PMID 34638331, 2021). "We also demonstrated that AP1S2 is a direct target of miR-204-5p in melanoma." (PMID 31712557, 2019). "We also found that miR-204-5p exerts its antimotility activity in melanoma by targeting AP1S2, and LICN00518 could bind to miR-204-5p." (PMID 31712557, 2019).
melanoma (continued). "AP1S2 is a validated target for promoting metastasis of melanoma cells." (PMID 31712557, 2019). "miR-204-5p was decreased and AP1S2 was increased in melanoma tissues." (PMID 31712557, 2019). "miR-204-5p mimics also repressed the level of AP1S2 mRNA and protein in melanoma cells." (PMID 31712557, 2019). "The expression of AP1S2 was increased in malignant melanoma cell." (PMID 31712557, 2019). "We confirmed the expression patterns of CLN6, GMPR, AP1S2, and ITGA6 in melanoma cells using gene-specific primers by qRT-PCR." (PMID 40821828, 2025). "Scratch wound assays and transwell assays showed that knockdown of AP1S2 and LINC00518 and overexpression of miR-204-5p significantly repressed the invasive and migratory ability of melanoma cells." (PMID 31712557, 2019). "Silencing of the new targets AP1S2, IGFBP5, and SOX11 resulted in reproducible effects on melanoma cell invasion and migration but strikingly, miR-211 alone did not influence proliferative and invasive growth characteristics significantly." (PMID 24039954, 2013). "These genes along with their activation values Eq for melanoma (MEL) are, GPNMB (MEL activation = 18.59), UBL3 (MEL activation = 1.39), AP1S2 (MEL activation = 1.28), RAB38 (MEL activation = 0.91), EDNRB (MEL activation = 0.55), JUN (MEL activation = 0.34), and C1orf21 (MEL activation = -0.13)." (PMID 34570764, 2021). "Migration was augmented up to 30 h of assay time for only AP1S2 and IGFBP5 in A375 melanoma cells." (PMID 24039954, 2013).
Hydrocephalus (6 papers, 2017 to 2024). Hydrocephalus is an active distension of the ventricular system of the brain resulting from inadequate passage of CSF from its point of production within the cerebral ventricles to its point of absorption into the systemic circulation. "Clinically, mutations in AP1S2 are commonly associated with Fried-Pettigrew syndrome, characterized by hydrocephalus, intellectual disabilities, mild facial anomalies, and basal ganglia calcification." (PMID 39839745, 2024). "AP1S2 gene pathogenic variants (MIM#300629) which cause hydrocephalus with mental retardation are associated with calcifications and iron deposits in the basal ganglia." (PMID 28460636, 2017). "AP1S2 is a component of adaptor protein complex 1, and AP1S2 mutation could cause various brain diseases, including hydrocephalus and Dandy-Walker malformation, among others." (PMID 33816256, 2021). "Pathogenic AP1S2 variants have been linked to Pettigrew syndrome characterized by intellectual disability with prominent basal ganglia iron deposition or calcification and variable severity of hydrocephalus." (PMID 34092257, 2021). "In some cases, AP1S2‐linked hydrocephalus was associated with stenosis of the Sylvian aqueduct." (PMID 30518636, 2019). "AP1S2 is also located in the X chromosome and, like L1CAM, underlies several syndromic defects, one of which is hydrocephalus." (PMID 30518636, 2019). "Although numerous genes have been found to be associated with the development of hydrocephalus in animal studies, only six genes have been definitively proven to be closely related to congenital hydrocephalus in humans: L1CAM, AP1S2, MPDZ, FOXJ1, SMARCC1, and CCDC88C." (PMID 39839745, 2024). "No causal connection has been made between AP1S2 LOF mutations and the formation of hydrocephalus." (PMID 30518636, 2019).
Intellectual disability (6 papers, 2008 to 2025). "According to many studies, AP1S2 mutations are associated with mental retardation, which is significant for genetic counseling and prenatal diagnosis." (PMID 40165344, 2025). "Syap1-deficient mice have been shown to display motor and movement defects; Ap1s2 has been associated with intellectual disability, basal ganglia disease, and seizures accompanying Pettigrew syndrome." (PMID 34034791, 2021). "(2015) reported that one out of 150 male patients with intellectual disability had mutations in AP1S2 mutation, so patients with ID should do AP1S2 detection." (PMID 30714330, 2019). "Mutation of AP1S2 protein is associated with X-linked Dandy–Walker malformation with intellectual disability, basal ganglia disease and seizures (Pettigrew syndrome)." (PMID 25844808, 2015). "Recently, mutations in the σ1B subunit of AP-1 (AP1S2) were identified in patients with X-linked mental retardation." (PMID 19057675, 2008). "AP1S1 mutations cause MEDNIK (mental retardation, enteropathy, deafness, peripheral neuropathy, ichthyosis, and keratoderma) syndrome; AP1S2 mutations are responsible for some forms of X-linked mental retardation; and AP1S3 mutations increase susceptibility to pustular psoriasis." (PMID 37108275, 2023).
Pettigrew syndrome (5 papers, 2015 to 2025). "Variants in the AP1S2 gene have been reported to cause a rare neurodevelopmental disorder, Pettigrew syndrome, characterized by delayed walking, abnormal speech, mild-to-severe XLID, and abnormal brain and behavioral features." (PMID 39928819, 2025). "Pettigrew syndrome (PGS) is a rare X‐linked mental retardation that caused by AP1S2 mutation." (PMID 30714330, 2019).
congenital hydrocephalus (4 papers, 2019 to 2023). Hydrocephalus that is present at birth. "AP1S2 encodes the sigma 2 subunit of the AP1 Adaptin protein for regulating lysosomal protein sorting, and the mutation of AP1S2 was reported to relate to X-linked congenital hydrocephalus through aberrant vesicle trafficking." (PMID 35047005, 2021). "The genes responsible for X-linked human congenital hydrocephalus are L1CAM (L1 protein), located at Xq28, and AP1S2." (PMID 35047005, 2021).
prostate carcinoma (2 papers, 2013 to 2021). A carcinoma that arises from epithelial cells of the prostate gland. "Another lncRNA in the top 10 best-selected features by the stratification of prostate cancer patients with known genomic alteration vs. unknown is lnc-AP1S2-2." (PMID 33672425, 2021). "Then, patients were stratified into two groups: prostate cancer with a known genomic alteration vs. unknown, and the co-expression analysis showed that three lncRNAs: lnc-SNX10-87, lnc-AP1S2-2 and ADPGK-AS1 have significant correlation values with other coding genes." (PMID 33672425, 2021).
bipolar disorder (1 paper, 2025). A disorder of the brain that causes unusual shifts in mood, energy, activity levels and the ability to carry out day-to-day tasks. "In bipolar disorder, we identified common oligodendrocyte-specific differentially acetylated peaks in the vicinity of AP1S2, SIL1, and EDAR, while controlling for CHAS scores and MF proportions, respectively." (PMID 40300607, 2025).
colon cancer (1 paper, 2024). "In colon cancer, adaptor related protein complex 1 subunit mu 1 (AP1M1), subunit sigma 2 (AP1S2), and subunit sigma 3 (AP1S3) are common overregulated genes and might be related to the accumulation of IFITM3 protein on the cell surface." (PMID 39228892, 2024).
neurodevelopmental disabilities (1 paper, 2019). "This study together with the previous reports can speculate that AP1S2 deficiency is associated with neurodevelopmental disabilities that lead to the phenotype observed in our patients." (PMID 30714330, 2019).
tumor (4 papers, 2021 to 2025). "The four-gene signature (CLN6, GMPR, AP1S2, ITGA6) and their validated roles in proliferation/migration (e.g., CLN6 knockdown suppressing tumor growth) provide novel therapeutic targets." (PMID 40821828, 2025). "Clusters 3 and 5, mainly enriched in the tumor and interface zones, were characterized by genes S100A4, AP1S2 and S100A6 that defined monocytes." (PMID 37644609, 2023). "Furthermore, differential analysis of tumor cells in the two single-cell datasets (high CDI vs. low CDI) found that all genes from the lysosome-dependent cell death gene set (BLOC1S1, AP1S2) were stable in both datasets." (PMID 39773329, 2025).
neurodevelopmental disorder (3 papers, 2019 to 2025). A behavioral and cognitive disorder with onset during the developmental period that involves impaired or aberrant development of intellectual, motor, or social functions. "Our findings suggest AP1S2 mutations contribute to a broad spectrum of neurodevelopmental disorders and are important in the etiological spectrum of PGS." (PMID 30714330, 2019). "The pedigree reported here had somewhat similar clinical findings with those reported by others, suggesting that AP1S2 contributes significantly to the broad spectrum of dysmorphic features and neurodevelopmental disorders seen in patients with AP1S2 mutation." (PMID 30714330, 2019). "Studies related to AP1S2 have mainly focused on its mutation in neurodevelopmental disorders 61-63." (PMID 31523167, 2019).
cancer (2 papers, 2021). A tumor composed of atypical neoplastic, often pleomorphic cells that invade other tissues. "In addition, AP1S2 downregulation inhibits cancer cell mobility in melanoma cells, suggesting that its regulation might be a target for treatment." (PMID 34565296, 2021). "Finally, similarly to that of AP1S2, the upregulation of AP1S3 was found to be linked with cancer cell aggressiveness among breast cancer patients and could be a target for small RNA silencing, which highlights its potential as a target for cancer treatment." (PMID 34565296, 2021). "Depletion of KIF13A or AP1S2 mitigates ZEB1-dependent focal adhesion dynamics, front-rear axis polarization, and cancer cell motility." (PMID 34732702, 2021).
infection (1 paper, 2023). The state of being infected such as from the introduction of a foreign agent such as serum, vaccine, antigenic substance or organism. "The regulatory networks miRNs–mRNA showed that FRS2 and AP1S2 target genes interacted with gga-miR-204 and gga-miR-1729-5p, while HHIP target gene is regulated by two miRNAs, gga-miR-19b-3p and gga-miR-132a-3p, at 7 days post-infection." (PMID 38288128, 2023).
AP1S2 also shares sentences with these, for which no sentence is quoted: epilepsy (2 papers); brain diseases (1); breast carcinoma (1); cataract (1); cutaneous melanoma (1); Dandy-Walker malformation (1); deafness (1); Duchenne muscular dystrophy (1); enteropathy (1); Hypermetropia (1); ichthyosis (1); inflammatory bowel disease (1); intellectual impairment (1); lung carcinoma (1); metastatic melanoma (1); movement disorder (1); nephrotic syndrome (1); neuroblastoma (1); Neurological Disorder (1); osteosclerosis (1); peripheral neuropathy (1); pulmonary diseases (1); pustular psoriasis (1); Strabismus (1); Tetralogy of Fallot (1).